ICAM1 (intercellular adhesion molecule 1)
Diseases named in the same sentence as ICAM1 in open-access papers (continued):
Sharing a sentence is not in itself a finding about the gene and the disease.
atherosclerosis (continued). "Thrombin-cleaved PAR1 was associated with increased plasma biomarkers such as VCAM1, ICAM-1, and E-selectin in 190 high-risk patients (CRP of mg/L 7.4 ± 6.7 mean ± SD) with chronic CVD due to atherosclerosis." (PMID 34944024, 2021). "ET-1, vWF, and ICAM-1 are all biomarkers of endothelial dysfunction and implicate atherosclerosis progression." (PMID 34484820, 2021). "Intercellular adhesion molecule-1 (ICAM-1) and vascular cell adhesion molecule-1 (VCAM-1) are considered important risk factors involved in the development of atherosclerosis." (PMID 34388961, 2021). "Another m6A writer, METTL14, has been shown to interact with FOXO1 and act directly on the promoter regions of VCAM-1 and ICAM-1, which enhanced the binding of monocytes to endothelial cells during atherosclerosis." (PMID 34869371, 2021). "The increased expression of the adhesion molecule ICAM-1 can enhance the adhesion and transfer ability of macrophages, which is also a prerequisite for atherosclerosis." (PMID 34931926, 2021). "Overall, we herein found that HUVECs express high levels of G2A, which is thus a promising biomarker of atherosclerosis that can mediate the LPC-induced upregulation of ICAM-1/VCAM-1 via Gi-independent mechanisms." (PMID 34346841, 2021). "Asiaticoside has been found to reduce endothelial permeability; it can effectively protect the occurrence of atherosclerosis by lowering the levels of intercellular adhesion molecule-1, vascular cell adhesion molecule-1, and E-selectin." (PMID 33013406, 2020). "The adhesion molecules, vascular cell adhesion molecule-1 (VCAM-1) and intercellular adhesion molecule-1 (ICAM-1) are involved in the attraction and tethering of leukocytes to the blood vessel wall, thus have a role in both early and on-going atherosclerosis." (PMID 31923583, 2020). "As an endothelial-leukocyte adhesion molecule, ICAM-1 expression level increases in atherosclerosis lesions." (PMID 32300482, 2020). "High expression levels of cell adhesion molecules (CAMs) such as VCAM-1, ICAM-1, and E-selectin by vascular endothelium are well correlated with atherosclerosis." (PMID 32066426, 2020). "For example, while our data showed little α-2,3-sialylated ICAM-1 in human atherosclerosis, it was present in failed AVFs from humans." (PMID 32208424, 2020). "ICAM-1 is a marker for vascular inflammation in atherosclerosis, which can be found significantly increased in atherosclerotic plaques." (PMID 33276745, 2020). "Inflammatory stimuli increased the expression of the adhesion molecules E-selectin, VCAM-1, and ICAM-1 in endothelial cells, leading to increased adhesion of monocytes to the endothelium, which is one of the initial steps in the development of atherosclerosis." (PMID 32802173, 2020). "A cohort study performed in adults with atherosclerosis reported that high plasma levels of EPA and EPA + DHA were associated with lower levels of soluble forms of intercellular cell adhesion molecule (ICAM)-1 in participants who were obese." (PMID 33187281, 2020). "Attempts to therapeutically target ICAM-1 to abrogate atherosclerosis in vivo have been successful in animal models; for example, ICAM-1 deficiency and anti-ICAM-1 antibody treatment protects against atherosclerosis in ApoE-deficient mice." (PMID 32208424, 2020). "ICAM-1 is enriched in macrophages in advanced plaques and contributes to plaque formation in mouse models of atherosclerosis." (PMID 32852032, 2020). "Endothelial cell expression of VCAM-1 and ICAM-1 trigged by disturbed flow is one of the earliest events in atherosclerosis development preceding the presence of other markers of atherosclerosis such as monocyte recruitment." (PMID 31584065, 2020). "Activated endothelial cells at sites of early atherosclerosis have been reported to show increased expression of P-selectin, ICAM-1, and VCAM-1." (PMID 33339328, 2020).
atherosclerosis (continued). "Adhesion and inflammatory molecules, such as VCAM-1 and intercellular adhesion molecules-1 (ICAM-1), are crucial players in the progression of atherosclerosis." (PMID 33510642, 2020). "Double and triple treatment decreased endothelial expression of ICAM-1 and consequently reduced monocyte adhesion to the activated vascular endothelium, well-recognized processes in the initiation of atherosclerosis." (PMID 31843957, 2020). "Sequentially, monocyte adhesion to endothelial cells was a crucial step in the early stages of atherosclerosis development, in which ICAM-1 and VCAM-1 were crucially involved." (PMID 33425996, 2020). "ICAM-1 “adheres” to leukocyte integrin, which aids in leukocytes migration to the damaged intima, leading to atherosclerosis." (PMID 31783796, 2019). "Evidence implicating ICAM-1 in the pathogenesis of atherosclerosis and CHD come from both human and animal studies." (PMID 30674642, 2019). "VCAM-1 and ICAM-1 have similar structures, but they are regulated by different mechanisms and show different functions at the initiation of lesions of atherosclerosis." (PMID 31452653, 2019). "In this study both ICAM-1 and VCAM-1 were correlated with risk for future CVD and ICAM-1 also with subclinical atherosclerosis, in line with previous studies." (PMID 31381601, 2019). "Cell adhesion molecule-1 (CAM-1) is very common in human atherosclerotic plaques and can be regulated by various stimuli, suggesting that ICAM-1 plays a role in atherosclerosis." (PMID 30838022, 2019). "Our finding adds to the growing body of evidence implicating that both expression and serum levels of ICAM-1 had an important role in pathogenesis of atherosclerosis as well as PCOS." (PMID 31629408, 2019). "Endothelial markers, ICAM-1 and VCAM-1, are implicated in atherosclerosis and associated with cardiovascular risk." (PMID 31370809, 2019). "Silencing of DNMT-1 by adenovirus-mediated DNMT shRNA inhibits the expressions of EC dysfunction-related proteins, including proliferating cell nuclear antigen, VCAM-1, and ICAM-1, and blocks the development of atherosclerosis." (PMID 31387590, 2019). "VCAM-1 and ICAM-1 are induced in disease status including inflammation, atherosclerosis, vascular injury, and angiogenesis." (PMID 31575085, 2019). "Here, we report that all three isoforms of ShcA are required to decrease eNOS expression levels, to increase ICAM-1 expression, and promote cell adhesion molecules and atherosclerosis." (PMID 29540796, 2018). "For instance, beta-sitosterol, a common ingredient of Arum ternatum Thunb and Zingiber officinale Roscoe, has inhibitory effects on the expression of VCAM-1 and ICAM-1, which promote atherosclerosis by regulating the chronic inflammatory process." (PMID 29861771, 2018). "An important early step in the process of atherosclerosis is the adhesion of monocytes to activated endothelial cells, in which various adhesion molecules including ICAM1 are involved." (PMID 29535705, 2018). "Immune cells derived IL-6 and TNF-α induce endothelium damage and increased expression of vascular cell adhesion molecule-1 (VCAM-1) and intercellular adhesion molecule-1 (ICAM-1), consequently triggering atherosclerosis development." (PMID 30305178, 2018). "Our prior study found that P. gingivalis infection induced ICAM-1 expression and monocyte recruitment, which are crucial events leading to atherosclerosis pathogenesis." (PMID 29482504, 2018). "Other studies have shown that partial inhibition of endothelial activation by knockdown of E-selectin, P-selectin, ICAM-1 or MCP-1 attenuates atherosclerosis development in mice." (PMID 30273401, 2018). "In response to inflammatory stimuli, vascular endothelial cells express a number of adhesion molecules that mediate early leukocyte attachment and atherosclerosis progression, particularly, such as ICAM1, VCAM1 and E‐selectin." (PMID 29512862, 2018).
atherosclerosis (continued). "A significant amount of research suggests that ICAM-1 plays a pivotal role in the development of atherosclerosis." (PMID 29696063, 2018). "Studies have shown that increased intercellular adhesion molecule − 1 (ICAM-1) expression is one of the molecular mechanisms of the pathological changes during the early stage of atherosclerosis." (PMID 29482504, 2018). "Upregulation of miR-155 can promote several pro-inflammatory processes, including leukocyte adhesion to the endothelium by enhancing the expression of VCAM-1 and ICAM-1, leading to atherosclerosis." (PMID 29642385, 2018). "Accumulating evidence has suggested that MCP-1 and ICAM-1 stimulate the recruitment and firm adhesion of inflammatory cells to endothelial cells, thereby contributing to the develop and progression of atherosclerosis." (PMID 30174716, 2018). "In the Multi-ethnic Study of Atherosclerosis (MESA) study, continuous strong, positive associations between GGT and CRP, interleukin-6 (IL-6), and soluble intercellular adhesion molecule-1 (sICAM-1) were observed in multivariable models." (PMID 29491346, 2018). "In vivo, ICAM-1 has been shown to be necessary for aldosterone induction of atherosclerosis and vascular inflammation in the ApoE−/− model." (PMID 30038907, 2018). "Intercellular adhesion molecule–1 (ICAM1) is crucial to the development and progression of atherosclerosis." (PMID 28095483, 2017). "A circulating or soluble form of ICAM-1 with elevated levels were also observed in patients with atherosclerosis and heart failure." (PMID 28881754, 2017). "ICAM-1 overexpression and subsequent adhesion of leukocytes to endothelial cells play critical roles in the early stage of atherosclerosis." (PMID 29021525, 2017). "To determine the effect of P. gingivalis infection on expression of atherosclerosis-associated proteins, we measured expression of three adhesion molecules (E-selectin, VCAM1, and ICAM-1) in HUVECs at the transcriptional level using qRT-PCR." (PMID 27826542, 2016). "It has been reported that lycopene can inhibit TNF-α-induced ICAM-1 protein expression through affecting the NF-κB signaling pathway, which explains how lycopene has protective effects on allograft atherosclerosis through anti-inflammatory activity." (PMID 28050227, 2016). "Endothelial cells also express adhesion and chemoattractant molecules such as MCP-1, VCAM-1, and ICAM-1, which recruit inflammatory monocytes into the vascular wall and initiate atherosclerosis." (PMID 27190988, 2016). "Atherosclerosis PCR array and qPCR analyses showed upregulation of adhesion molecules such as intercellular adhesion molecule-1, vascular cell adhesion molecule-1, and E-selectin in HAECs upon SAA stimulation." (PMID 27799725, 2016). "Other important pathways for endothelial homeostasis that were disrupted included inflammatory pathways (for example, atherosclerosis, agranulocyte adhesion and diapedesis) represented by the upregulation of genes such as ICAM1, BMP4 and IL6." (PMID 26617239, 2015). "VCAM-1, and ICAM-1 and E-sel are well-known inflammatory mediators involved in pathogenesis of atherosclerosis." (PMID 25632270, 2015). "Increased levels of ICAM-1 and VCAM-1 have been associated with the early events of atherosclerosis." (PMID 26622474, 2015). "Specifically, ICAM1 rs281432 is an intronic SNP that has been studied in diabetes and subclinical atherosclerosis, although findings have been mixed." (PMID 25575156, 2015). "Further studies indicate that celecoxib treatment of mice with experimentally induced atherosclerosis and autoimmune encephalomyelitis or rats with colitis and lung injury decreases the expression of ICAM-1." (PMID 26513172, 2015). "Systemic levels of ICAM-1 and VCAM-1 are associated with intimal-medial thickness and the degree of atherosclerosis in hypertensive type-2 diabetic patients." (PMID 26622474, 2015).
atherosclerosis (continued). "One early phase of atherosclerosis involves the firm adhesion of inflammatory cells to ECs as well, whose process is mainly mediated by ICAM-1 and VCAM-1." (PMID 25582325, 2015). "ApoC-III also induces inflammation, via ICAM-1 expression and monocyte adhesion to endothelial cells, leading to atherosclerosis." (PMID 24454915, 2014). "The most important adhesion molecules involved in atherosclerosis appear to be endothelial cell selectin (E-selectin), intercellular cell adhesion molecule (ICAM)-1, and vascular cell adhesion molecule (VCAM)-1." (PMID 25045892, 2014). "Transcriptional screening of ACE-overexpressing monocytes revealed noticeably increased expression of Angiotensin II receptors and adhesion- as well as atherosclerosis-related ICAM-1 and VCAM1." (PMID 25003524, 2014). "PGRN also played a protective role in atherosclerosis through suppressing TNFα-induced expression of ICAM-1 and VCAM-1 in endothelial cells." (PMID 24651300, 2014). "A soluble ICAM-1 (sICAM-1) form of has been found in plasma and identified early stages of inflammation in atherosclerosis." (PMID 25045892, 2014). "Several markers, such as VCAM-1, ICAM-1, and von Willebrand factor antigen, have been shown to reliably indicate the increased activation of endothelial cells in atherosclerosis." (PMID 25374442, 2014). "One early phase of atherosclerosis involves the recruitment and firm adhesion of inflammatory cells to ECs, whose process is mediated by adhesion molecules such as ICAM-1." (PMID 23984879, 2013). "The study of ICAM-1 expression was reported by several authors in various models of atherosclerosis." (PMID 24062791, 2013). "VCAM-1 and ICAM-1 are thought to play an important role in the process of atherosclerosis by recruiting inflammatory cells, and they are both are upregulated by pro-atherogenic factors." (PMID 24364887, 2013). "Given the role of adhesion molecules in the pathogenesis of atherosclerosis, we investigated the effect of ICAM-1 and VCAM-1 in our present analysis." (PMID 23826202, 2013). "The endothelial expression of ICAM-1 is increased in atherosclerosis and in animal models of atherosclerosis." (PMID 24499567, 2013). "Damaged endothelial cells, arterial lesions from atherosclerosis experiment model and human all show increased expression of these molecules including E-sel, ICAM-1, VCAM-1 and MCP-1." (PMID 23895132, 2013). "Adhesion molecules such as VCAM-1 and ICAM-1 play a significant role in the process of atherosclerosis as they ensure the recruitment of inflammatory cells." (PMID 24062791, 2013). "Circulating endothelial adhesion molecules, VCAM-1 and ICAM-1, were supposed to be early markers of atherosclerosis." (PMID 22919307, 2012). "Proinflammatory cytokines and adhesion molecules, such as vascular cell adhesion molecule (VCAM)-1 and intercellular cell adhesion molecule (ICAM)-1, induce atherosclerosis by NF-κB activation." (PMID 22645626, 2012). "Local reactive oxygen species can also directly activate NFκB and stimulate the expression of NFκB-dependent genes, including genes of proinflammatory factors related to atherosclerosis, such as intercellular adhesion molecule 1 (ICAM-1)." (PMID 22811752, 2012). "Expression levels of VCAM-1 and ICAM-1 were largely studied in a mouse model of atherosclerosis, and these molecules were upregulated by a high-cholesterol diet in an animal model." (PMID 22645626, 2012). "In the atherosclerosis group there were significant increase between 0 times and end time for all ICAM-1, VCAM-1 and CRP." (PMID 21214952, 2011). "To further analyze cellular and molecular mediators in the progression of atherosclerosis, we quantified the amount of lipids, macrophages, T cells, as well as of the adhesion molecules ICAM-1 and VCAM-1 in plaques from the aortic sinus." (PMID 21042583, 2010).
atherosclerosis (continued). "Further, lipoxygenase pathway SNPs that were associated with measures of atherosclerosis were associated with markers of inflammation (CRP, ICAM-1) and calcification (MGP).Conclusions." (PMID 20592751, 2010). "The initial step in atherosclerosis is the adhesion of leukocytes to activated endothelial cells mediated by intercellular adhesion molecule-1 (ICAM-1)." (PMID 20940515, 2010). "Decreased atherosclerosis correlated with a strong down-regulation in the expression of adhesion molecules, such as VCAM-1 and ICAM-1, by p55 TNFR deficient endothelium." (PMID 19582157, 2009). "Moreover, the expression of FOXP1 was positively correlated with SESN3 and negatively correlated with CDKN2A, MMP9, and ICAM1 in human atherosclerosis plaques." (PMID 41355963, 2026). "Also, our results indicate that a marker of subclinical atherosclerosis, ICAM‐1, was directly correlated with the DNA damage marker, 8‐OHdG." (PMID 40739796, 2025). "ICAM1, MAP3K8 and TNFAIP3 are highly associated with the development of atherosclerosis." (PMID 40607379, 2025). "ICAM‐1 is expressed by the vascular endothelium, monocytes/macrophages, and lymphocytes and is demonstrated to be increased in both, healthy older adults and patients with pathological diseases, including hypertension, diabetes, and atherosclerosis." (PMID 41014054, 2025). "Atherosclerosis is initiated by the accumulation of oxidized low-density lipoprotein (oxLDL), which triggers endothelial cell activation and upregulation of adhesion molecules, such as intercellular adhesion molecule-1 (ICAM-1), VCAM-1, and P-selectin, etc.." (PMID 41011157, 2025). "Correspondingly, several reports have demonstrated that 4-PBA effectively attenuates monocyte recruitment byreducing ICAM-1 expression through the mechanistic target of rapamycin (mTOR) signaling pathway, ultimately contributing to a reduction in the pathogenesis of atherosclerosis." (PMID 40661788, 2025). "One of the most robust biomarkers in atherosclerosis detection is (ICAM-1)." (PMID 41470139, 2025). "Since ICAM-1 expression is elevated on endothelium in the aortas of ApoE−/− mice with atherosclerosis, we utilized the I-domain of LFA-1 (idLFA-1) as a payload to create nanocarriers given that I-domain (id) is responsible for mediating ICAM-1/LFA-1 interactions." (PMID 40630903, 2025). "In the early stages of atherosclerosis, endothelial cells are activated and express intercellular adhesion molecule-1 (ICAM-1) and vascular adhesion molecule-1 (VCAM-1), which attract lymphocytes and monocytes to bind and infiltrate the arterial wall, leading to an inflammatory reaction." (PMID 40606622, 2025). "Exercise-induced MECP2K271la may attenuate atherosclerosis in patients with metabolic disorders by suppressing vascular adhesion molecules (e.g., ICAM-1) and promoting anti-inflammatory pathways." (PMID 40331975, 2025). "Increased ICAM-1 levels may serve as a molecular marker for the development of atherosclerosis and clinical coronary heart disease." (PMID 38195507, 2024). "ICAM-1 and IL-8 are two key molecules responsible for the activation and the firm adhesion of monocytes to activated endothelial cells for the initiation of atherosclerosis." (PMID 38397822, 2024). "The authors suggest that CIMT and ICAM-1 may be used to detect early atherosclerosis in children and adolescents with T1DM." (PMID 39768295, 2024). "CNDs as low as 0.03 mg/mL significantly inhibited TNF-α-mediated expression of IL-8 and adhesion molecule ICAM-1, two key molecules that are responsible for the activation and the firm adhesion of monocytes to activated endothelial cells for the initiation of atherosclerosis." (PMID 38397822, 2024). "Endothelial dysfunction, characterized by the impaired function of the cells lining the blood vessels, is regarded as an early indicator of atherosclerosis development, often identified by an increased expression of adhesion molecules such as ICAM-1 and VCAM-1." (PMID 38915995, 2024).